RYR1 (ryanodine receptor 1)
Diseases named in the same sentence as RYR1 in open-access papers (continued):
Sharing a sentence is not in itself a finding about the gene and the disease.
alveolar rhabdomyosarcoma (1 paper, 2023). A rapidly growing malignant mesenchymal neoplasm. "We presented the case of a patient with MH, cores, and alveolar rhabdomyosarcoma with a germline RYR1 pathogenic variant and a germline VUS in the ASPSCR1 gene." (PMID 37510264, 2023). "Here, we report the case of a patient with an RYR1 pathogenic variant associated with MH and cores who developed an alveolar rhabdomyosarcoma associated with a germline variant in the cancer predisposition gene ASPSCR1 (Alveolar Soft Part Sarcoma Chromosomal Region Candidate 1)." (PMID 37510264, 2023).
alveolar soft part sarcoma (1 paper, 2023). An alveolar soft part sarcoma occurring in adults. "Molecular analysis using NGS sequencing identified germline variants in the RYR1 and ASPSCR1 (alveolar soft part sarcoma) genes." (PMID 37510264, 2023).
amyotrophic lateral sclerosis (1 paper, 2022). Amyotrophic lateral sclerosis (ALS) is a neurodegenerative disease characterized by progressive muscular paralysis reflecting degeneration of motor neurons in the primary motor cortex, corticospinal tracts, brainstem and spinal cord. "Moreover, several potential disease-causing genes were detected and markedly enriched in the pathways of neurodegeneration (including WNT16, RYR3 and RYR1 genes) and amyotrophic lateral sclerosis (ALS, including NUP205, CAPN2, and NUP214 genes)." (PMID 35355568, 2022).
atrial fibrillation (1 paper, 2025). A disorder characterized by an electrocardiographic finding of a supraventricular arrhythmia characterized by the replacement of consistent P waves by rapid oscillations or fibrillatory waves that vary in size, shape and timing and are accompanied by an irregular ventricular response. "Despite these challenges, we did observe significant associations with atrial fibrillation/flutter, further reinforcing the relevance of RYR1 in cardiac disease progression." (PMID 40060969, 2025). "Furthermore, we provide evidence that genetic variants in RYR1 that are correlated with reduced RYR1 expression are also associated with improved survival in HF patients and potentially decreased risk of developing atrial fibrillation/flutter." (PMID 40060969, 2025).
atrial tachycardia (1 paper, 2019). A disorder characterized by an electrocardiographic finding of an organized, regular atrial rhythm with atrial rate between 101 and 240 beats per minute. "A girl with severe congenital RYR1-related myopathy exhibited atrial tachycardia and sinus node dysfunction during infancy." (PMID 31856875, 2019). "Here we report a girl with severe congenital RYR1-related myopathy who exhibited atrial tachycardia and sinus node dysfunction without cardiomyopathy during infancy." (PMID 31856875, 2019).
autism spectrum disorder (1 paper, 2025). A spectrum of developmental disorders that includes autism, and Asperger syndrome. "Some RYR1 de novo variants, such as p.(Arg3672His), p.(Asn4036Asp), and p.(Thr5005Ala), have been found to be associated with neurological disorders including autism spectrum disorder." (PMID 40430072, 2025).
autoimmune disease (1 paper, 2021). A disorder resulting from loss of function or tissue destruction of an organ or multiple organs, arising from humoral or cellular immune responses of the individual to their own tissue constituents. "Stimulatory and inhibitory effects of the gain-of-function RYR1-p.R163C mutation in EAE may explain an absence of association of this mutation with inflammatory and autoimmune diseases in humans." (PMID 35027891, 2021).
basal cell carcinoma (1 paper, 2022). A carcinoma involving the basal cells. "The expression of CACNA1S, ATP2A1, RYR1, and MYLK3 was upregulated in MAC compared with normal sweat glands and syringoma tumor cells and was generally negative in trichoepithelioma and infundibulocystic type basal cell carcinoma." (PMID 35509066, 2022). "We demonstrated that the CACNA1S, MYLK3, RYR1, and ATP2A1 proteins were more highly expressed in MAC tumor cells than in normal sweat glands and syringoma, while were generally negative in tumor cells of trichoepithelioma and basal cell carcinoma, infundibulocystic type." (PMID 35509066, 2022).
bent spine syndrome (1 paper, 2021). "Predominant axial myopathy had been reported in 12 RYR1-mutated patients, presenting between the third and eighth decade of life and suggesting RYR1 as a possible cause of idiopathic camptocormia or bent spine syndrome." (PMID 34208776, 2021).
bipolar disorder (1 paper, 2025). A disorder of the brain that causes unusual shifts in mood, energy, activity levels and the ability to carry out day-to-day tasks. "RYR1 variants have previously been associated with bipolar disorder." (PMID 40430072, 2025). "Genes encoding calcium channels, such as RYR1 and CACNA1D, have been identified as risk loci for bipolar disorder due to their roles in calcium signaling and the regulation of circadian rhythms." (PMID 40430072, 2025).
bladder cancer (1 paper, 2023).
caveolinopathy (1 paper, 2023). A group of muscle diseases with basis in CAV3, which encodes caveolin-3, a muscle-specific membrane protein and the principal component of caveolae membrane in muscle cells in vivo. "In agreement, it was shown that myotubes from caveolinopathy patients present a reduction in both depolarization-induced Ca2+ release and influx with disarrays in the colocalization of the DHPR and RyR1, thereby reducing the efficiency of excitation-contraction coupling." (PMID 37083699, 2023).
colon adenocarcinoma (1 paper, 2022). "The average number of RyR2 mutations per person was generally higher than that for RYR1 and RYR3, mostly strikingly in LUAD, LUSC and colon adenocarcinoma (COAD)." (PMID 36167878, 2022).
cystic hygroma (1 paper, 2016). A benign lymphatic neoplasm usually arising from the neck and characterized by cystic dilation of the lymphatic vessels. "Whole exome sequencing studies have identified novel compound heterozygous mutations in RYR1 in two affected foetuses with pterygium, severe arthrogryposis and foetal hydrops with cystic hygroma, characteristic features compatible with LMPS." (PMID 26932181, 2016).
developmental delay (1 paper, 2019). "Severe loss-of-function mutations in the mouse Ryr1 ortholog can result in paralysis and dominant mutations in the mouse can affect multiple organs in a syndrome interpreted as developmental delay." (PMID 31383689, 2019).
Dyskinesia (1 paper, 2017). A movement disorder which consists of effects including diminished voluntary movements and the presence of involuntary movements. "Other polymorphisms including rs886292 (ABCC8), rs11880894 (RYR1), rs1800497 (DRD2), rs6265 (BDNF), rs11646587, rs7192557 and rs8057394 (GRIN2A) were found to be associated with dyskinesia in patients administered with levodopa medication." (PMID 28927418, 2017). "Among South Asian (SAS) population, Israelis were most abundantly studied representing association of rs393795 (DAT1), rs886292 (ABCC8), rs11880894 (RYR1) and rs1800497 (DRD2) with dyskinesia." (PMID 28927418, 2017).
experimental autoimmune encephalomyelitis (1 paper, 2021). An autoimmune demyelinating disease of the central nervous system that is produced experimentally in animals by the injection of homogenized brain or spinal cord in Freund's adjuvant. "Here we studied how modulation of RyRs through administration of RyR inhibitor dantrolene or introducing a gain-of-function RYR1-p.R163C mutation affects clinical progression of experimental autoimmune encephalomyelitis (EAE) in mice, a T cell-mediated autoimmune neuroinflammatory disease." (PMID 35027891, 2021).
fetal hydrops (1 paper, 2024). "However, in this study, we only focused on the shearing variant caused by the RYR1 gene mutation, and there may be other factors involved in the mechanism of fetal hydrops, and we also need further studies to validate these findings to develop a more comprehensive and accurate therapeutic regimen." (PMID 39211906, 2024).
Friedreich ataxia (1 paper, 2021). An inherited condition that affects the nervous system and causes movement problems. "Other conditions that more frequently present in children with peculiar phenocopies include Friedreich’s Ataxia, myotonic dystrophy (congenital form), Kearns Sayre, RYR1 associated defects, and Laminopathies." (PMID 34827576, 2021). "In this review, we selected and described five specific NMDs: Friedreich’s Ataxia (FRDA), congenital and childhood forms of Myotonic Dystrophy type 1 (DM1), Kearns Sayre Syndrome (KSS), Ryanodine receptor type 1-related myopathies (RYR1-RM) and Laminopathies." (PMID 34827576, 2021).
gastric cancer (1 paper, 2022). A primary or metastatic malignant neoplasm involving the stomach. "Similarly, ryanodine receptor 1 (Ryr-1), another protein that is mostly present in skeletal muscles and referred to as the skeletal muscle calcium release channel or the skeletal muscle-type ryanodine receptor, is also linked to vasodilation, antioxidation, and gastric cancer." (PMID 36292625, 2022).
gastric ulcer (1 paper, 2022). An ulcerated lesion in the mucosal surface of the stomach. "Downregulation of Srm, Ryr-1, Eno3, Prkag3, and Eef1a2 genes involved in regulating arginine and proline metabolism, calcium signaling pathway, HIF-1 signaling pathway, oxytocin signaling pathway, and legionellosis are possibly involved in MD-4-mediated protection against gastric ulcers." (PMID 36292625, 2022).
hereditary amyloidosis (1 paper, 2025). Hereditary amyloidosis refers to a group of inherited conditions that make up one of the subtypes of amyloidosis. "Most represented variants for TTR-related hereditary amyloidosis (n = 17, 0.43%) and RYR1-related malignant hyperthermia (n = 13, 0.33%)." (PMID 40332002, 2025).
hydrops (1 paper, 2024). "Existing studies have also found that mutations in the RYR1 gene, as well as mutation-induced purebred shear variants, can be associated with fetal hydrops." (PMID 39211906, 2024). "Here, we report a novel heterozygote intronic variant affecting RYR1 gene splicing may cause fetal hydrops." (PMID 39211906, 2024).
Hyperglycemia (1 paper, 2022). An increased concentration of glucose in the blood. "We support our postulate based on the fact that muscle cells of RYR1-p.163C (model of malignant hyperthermia) and db/db (T2D model) with chronic elevated [Ca2+]i show reduced glucose uptake and hyperglycemia independent of genetic background." (PMID 35547584, 2022).
Hypokalemia (1 paper, 2019). An abnormally decreased potassium concentration in the blood. "Another patient carrying heterozygous RYR1 variant p.Ala4143Val complained of recurrent muscle weakness in proximal lower limbs with hypokalemia since 24 years old with a frequency of 2–3 times per year." (PMID 31068157, 2019).
insulinoma (1 paper, 2015). "Thimerosal, an oxidizing agent that effectively enhances the activity of skeletal RyR1 and cardiac RyR2 channels, releases Ca2+ from InsP3-insensitive ER Ca2+ pools in RINm5F insulinoma cells and from β-cells isolated from ob/ob mice." (PMID 26046640, 2015).
kidney damage (1 paper, 2025). "The early identification of RYR1 mutations in at-risk individuals may facilitate preventive strategies, such as exercise modifications and the avoidance of triggers, to mitigate kidney damage and improve long-term renal outcomes." (PMID 40429823, 2025).
Kyphosis (1 paper, 2010). Exaggerated anterior convexity of the thoracic vertebral column. "SNPs in KCNN2 on SSC2, RYR1 and PLOD1 on SSC6 and MYST4 on SSC14 were significantly associated with kyphosis in the resource population of swine (P ≤ 0.05)." (PMID 21176156, 2010).
lymphedema (1 paper, 2021). Excess fluid collection in tissues, causing swelling. "However, DANT has not received attention as an anti-lymphedema therapeutic, largely because the contribution of RYRs to lymph muscle contraction is regarded as minimal and the identity of the RYR subtypes (RYR1, RYR2, and RYR3) expressed by LMCs is unresolved." (PMID 34483938, 2021).
metastatic tumors (1 paper, 2026). "Intersection of significantly mutated genes with differentially expressed genes identified a focused 29-gene overlap, including RYR1 and ZNF273, that marks these convergent axes and distinguishes metastatic from non-metastatic tumors." (PMID 41573907, 2026).
mood disorder (1 paper, 2025). A cognitive disorder a disturbance in which the person's mood is hypothesized to be the main underlying feature. "Repeated administration of oligonucleotides that are antisense to the Ryr1 sequence resulted in an antidepressant-like response in mice, evidencing the significance of RYR1 as a crucial target in the context of mood disorders." (PMID 40430072, 2025).
neuroleptic malignant syndrome (1 paper, 2022). Neuroleptic malignant syndrome (NMS) is an idiosyncratic condition associated with administration of antipsychotic and other central dopaminergic blockers, and characterized by hyperthermia, muscular rigidity, autonomic dysfunction and altered consciousness. "Alternative phenotypic manifestations of RYR1 variants have been speculated as predisposing to neuroleptic malignant syndrome (NMS), serotonin syndrome, stimulant abuse, parkinsonism-hyperpyrexia syndrome, sepsis, toxicity of uncoupling agents dinitrophenol and aspirin, and others." (PMID 36123618, 2022).
Noonan syndrome (1 paper, 2021). Noonan Syndrome (NS) is characterized by short stature, typical facial dysmorphism and congenital heart defects. "In our cohort of fetuses, the CDG-2m, RyR1-related myopathy, Noonan syndrome, and possibly the mosaic PAX6 duplication might have been detected with prenatal WES." (PMID 34733861, 2021).
Obesity (1 paper, 2017). Accumulation of substantial excess body fat. "In fact, this effect on the RYR1 promoter is the most prominent methylation response to obesity, most heavily affected." (PMID 28919880, 2017).
oral cavity squamous cell carcinoma (1 paper, 2026). A squamous cell carcinoma arising from the oral cavity. "Moreover, RYR1 mutational status correlates with TMB as panel variable for survival prediction in surgically treated patients with oral cavity squamous cell carcinoma." (PMID 41541656, 2026).
Osteopenia (1 paper, 2025). Osteopenia is a term to define bone density that is not normal but also not as low as osteoporosis. "Serum RYR1 concentration was found to be higher in osteopenia and osteoporosis groups." (PMID 41440556, 2025).
osteoporosis (1 paper, 2025). A condition of reduced bone mass, with decreased cortical thickness and a decrease in the number and size of the trabeculae of cancellous bone (but normal chemical composition), resulting in increased fracture incidence. "Two previous studies have reported that individuals with RYR1-related disorders (arrhythmias and myopathies) have bone problems such as scoliosis and osteoporosis at an early age." (PMID 41440556, 2025).
papillary thyroid cancer (1 paper, 2022). "Finally, we investigated the expression levels of the common mutated genes (JMJD1C, MUC16, PDZD2, RYR1, and SLA) in papillary thyroid cancer cell lines (K1, TPC-1 and BCPAP) compared to an immortalized normal thyroid epithelial cell line (Nthy-ori 3-1) by qRT-PCR." (PMID 35996174, 2022).
Paralysis (1 paper, 2018). Paralysis of voluntary muscles means loss of contraction due to interruption of one or more motor pathways from the brain to the muscle fibers. "Three cases with episodic muscle paralysis or weakness and additional findings compatible with a RYR1-related myopathy were identified." (PMID 29298851, 2018).
paraplegia (1 paper, 2021). Complete paralysis of the lower half of the body including both legs, often caused by damage to the spinal cord. "Mutations in SPG7 and RYR1 genes are associated with muscle developmental impairment causing paraplegia and myopathy, respectively." (PMID 34125832, 2021).
Parkinson disease (1 paper, 2022). A progressive degenerative disorder of the central nervous system characterized by loss of dopamine producing neurons in the substantia nigra and the presence of Lewy bodies in the substantia nigra and locus coeruleus. "CPNQ targets huntingtin and α-synuclein to lower their pathological effects in cellular models of Huntington’s and Parkinson’s diseases, respectively, and we show here that this compound significantly inhibited only RyR1 (with an inhibitory trend on RyR2) at low [Ca2+]." (PMID 34793835, 2022).
peanut allergy (1 paper, 2022). "Additional signals of shared selection signatures were found in RYR1, where the variant rs3786829 was associated with peanut allergy, another SNP was found in DENND1A, the variant carrying the signal (rs2479106) was associated with polycystic ovary syndrome." (PMID 36131251, 2022).
primary cardiomyopathies (1 paper, 2007). "Although cardiac impairment secondary to respiratory involvement is not uncommonly observed in SEPN1-related MmD, primary cardiomyopathies have not been reported in genetically confirmed cases of MmD due to mutations in the SEPN1 or RYR1 genes." (PMID 17631035, 2007). "It is likely that the few families with primary cardiomyopathies in association with minicores on muscle biopsy reported in the pre-molecular area may have carried mutations in above genes rather than the SEPN1 and RYR1 genes now firmly associated with MmD." (PMID 17631035, 2007).
prion disease (1 paper, 2023). A transmissible disease that is caused by a protein that is able to induce abnormal folding of normal cellular proteins, leading to characteristic spongiform brain changes, which are associated with neuronal loss without an inflammatory response. "Other noteworthy hub-hub genes, including CKM, RYR1, and VWF, presented lower expression in LDM tissue and have critical roles in metabolic pathways, oxytocin signaling pathway, ECM-receptor interaction, prion disease, and calcium signaling pathway." (PMID 37627391, 2023).
psychosis (1 paper, 2025). "Taken together with our previous results, and excluding RYR1, we have potential candidates for patients in five families with psychosis." (PMID 40430072, 2025). "Our research indicates a need for further evaluation of INSR, NFXL1 and possibly RYR1 in psychosis in humans." (PMID 40430072, 2025).
pulmonary hypertension (1 paper, 2025). Increased pressure within the pulmonary circulation due to lung or heart disorder. "A transcriptome-wide analysis revealed RYR1 upregulation in HF patients with severe pulmonary hypertension." (PMID 40060969, 2025).
rhabdomyosarcoma (1 paper, 2023). A rare aggressive malignant mesenchymal neoplasm arising from skeletal muscle. "So far, there is no reported link between RYR1 gene mutations and rhabdomyosarcoma development." (PMID 37510264, 2023).
steatosis (1 paper, 2024). Increased lipid within the cytoplasm of cells. "RYR1 gene mutations are frequently found in both mouse and human NASH-HCC, indicating dysregulation of calcium signaling in cholesterol-related NASH-HCC and NASH rather than steatosis." (PMID 39359475, 2024).
Stormorken syndrome (1 paper, 2022). Stormorken-Sjaastad-Langslet syndrome is characterized by thrombocytopathy, asplenia, miosis, muscle fatigue, migraine, dyslexia, and ichthyosis. "The recent identification of tubular aggregates, a hallmark of TAM/Stormorken syndrome, in patients carrying RYR1 mutations represents only the latest evidence of how complex it is to associate genetic data and histopathological patterns." (PMID 35980353, 2022). "Therefore, considering the quite mild phenotype reported, patients with TAM associated with RYR1 mutations may represent the less severe side of the TAM/Stormorken syndrome." (PMID 35980353, 2022).